HNRNPA1P33 (heterogeneous nuclear ribonucleoprotein A1 pseudogene 33)
Gene: Processed pseudogene on chromosome 10 (46,415,853 to 46,416,413, forward strand). Ensembl gene ENSG00000213412.
Diseases named in the same sentence as HNRNPA1P33 in open-access papers:
HNRNPA1P33 is named in the same sentence as 3 diseases in open-access papers, as found by Europe PMC text mining. Sharing a sentence is not in itself a finding about the gene and the disease. The quoted sentences say what the papers report.
cancer (2 papers, 2017 to 2020). A tumor composed of atypical neoplastic, often pleomorphic cells that invade other tissues. "HnRNP genes demonstrated heterogeneous distributions in different cancer types: HNRNPA1 and HNRNPAB were highly expressed in most tumours; HNRNPA1P33 expression was increased in COAD, READ and LUAD whereas decreased in CHOL, PRAD and BLCA." (PMID 32915499, 2020). "Seven (PA2G4P4, ATP5EP2, FTH1P3, ANXA2P3, ANXA2P1, HNRNPA1P33, and HSP90B3P) of the 14 pseudogenes that our analysis revealed as important for pan-cancer classification were previously found to be differentially expressed in various cancers." (PMID 28673244, 2017).
tumours (1 paper, 2020). "Moreover, HNRNPA1P33 expression was increased in COAD, READ and LUAD whereas decreased in CHOL, PRAD and BLCA, which indicated that hnRNPs might exert different functions in diverse kinds of tumours." (PMID 32915499, 2020).
HNRNPA1P33 also shares sentences with these, for which no sentence is quoted: Esotropia (1 paper).